SYCP3 (synaptonemal complex protein 3)
Description:
Component of the synaptonemal complexes (SCS), formed between homologous chromosomes during meiotic prophase. Required for centromere pairing during meiosis in male germ cells (By similarity). Required for normal meiosis during spermatogenesis and male fertility. Plays a lesser role in female fertility. Required for efficient phosphorylation of HORMAD1 and HORMAD2 (By similarity).
Synonyms: SCP3; COR1; RPRGL4; SPGF4
Tractability: PROTAC: ubiquitination databases record sites on it.
Gene: Protein-coding gene on chromosome 12 (101,728,648 to 101,739,472, reverse strand). Ensembl gene ENSG00000139351.
Subcellular location: Nucleus; Chromosome; Chromosome, centromere
Pathways (Reactome):
Reproduction: Meiotic synapsis
Gene Ontology:
Molecular function: protein binding
Biological process: sperm DNA condensation; homologous chromosome pairing at meiosis; homologous recombination; male meiosis I; meiotic cell cycle; reciprocal meiotic recombination; spermatid development
Cellular component: nucleus; synaptonemal complex; chromosome; chromosome, centromeric region; condensed nuclear chromosome; lateral element
Genetic constraint (gnomAD): Loss-of-function variants: 22 observed, 29.55 expected, observed/expected ratio (o/e) 0.74, 90% interval 0.53 to 1.06. The upper end of that interval is the gene's LOEUF score, 1.06, which puts it in group 4 of 6, group 1 being the genes least tolerant of losing a copy. Missense variants: 200 observed, 234.93 expected, observed/expected ratio (o/e) 0.85, 90% interval 0.76 to 0.96. Synonymous variants: 64 observed, 71.79 expected, observed/expected ratio (o/e) 0.89, 90% interval 0.73 to 1.1.
Homologues: Orthologues: chimpanzee SYCP3 (100% identical), macaque SYCP3 (99% identical), pig SYCP3 (84% identical), rat Sycp3 (72% identical), mouse Sycp3 (72% identical), rabbit SYCP3 (65% identical), tropical clawed frog sycp3 (64% identical), guinea pig SYCP3 (58% identical), zebrafish sycp3 (56% identical), mouse 1700013H16Rik (36% identical), rat Fam9b (35% identical), rat 3830403N18Rikl (32% identical), and 104 more. Paralogues in human: FAM9A (25% identical), FAM9B (22% identical), FAM9C (20% identical).
Diseases named in the same sentence as SYCP3 in open-access papers:
SYCP3 is named in the same sentence as 30 diseases in open-access papers, as found by Europe PMC text mining. Sharing a sentence is not in itself a finding about the gene and the disease. The quoted sentences say what the papers report.
Infertility (16 papers, 2009 to 2025). "Four genes with the most observed LoF variants are SYCE1, C14ORF39, SYCP2, and SYCP3, corresponding to the four reported genes with infertility-related mutations." (PMID 35342360, 2022). "Sycp3 gene knockout causes infertility in male mice and reduced fertility in females, due to aneuploidy in oocytes and ensuing embryonic lethality, and a mutation that renders SYCP3 defective causes human male infertility." (PMID 31615332, 2019). "SYCP3 also shows a high mutation frequency in infertile patients." (PMID 35342360, 2022). "However, autosomal dominant monogenic mutations can also precipitate a state of infertility including SYCP3 (Synaptonemal complex protein 3), NR5A1 (nuclear receptor subfamily 5 group A member 1) and the WT1 (Wilms' tumor 1) gene." (PMID 33101214, 2020). "In human testes, synaptonemal complex protein 3 (SYCP3) depletion strongly correlates with disruption of early spermatogenesis and infertility." (PMID 40857739, 2025). "So far, infertility-related SC gene mutations are limited to four SC genes (SYCP2, SYCP3, C14ORF39, and SYCE1)." (PMID 35342360, 2022). "So far, infertility-related mutations have been identified in four SC coding genes, including SYCP2, SYCP3, SYCE1, and C14ORF39." (PMID 35342360, 2022). "Fbxw24‐KO caused delayed SYCP3 degradation and unrepaired DSB from pachytene until MII, ultimately leading to defective oocyte maturation and infertility." (PMID 35858239, 2022). "STRING and Cytoscape analyses presented seven genes, i.e., DDX5, TNP2, DDX3Y, TDRD6, SOHL2, DDX31, and SYCP3, as the hub genes involved in infertility with VASA co-function and protein–protein interaction." (PMID 36241908, 2022). "FBXW24‐KO delayed SYCP3 degradation and DSB repair from pachytene until metaphase II (MII), ultimately causing failure in oocyte maturation, oocyte death, and infertility." (PMID 35858239, 2022). "In the case of our patient, if SYCP3 is the only gene responsible for infertility, then the xenotransplantation of patient-specific iPSCs into mouse testis should induce PGC-like development." (PMID 28045072, 2017). "We identified SYCP3 (synaptonemal complex protein 3) as a potential candidate gene responsible for his infertility." (PMID 28045072, 2017). "The infertility of Cfp1Stra8 mice was attributed to meiotic arrest, in which aberrant formation of lateral and central elements resulting in patchy staining of Sycp1 and Sycp3 was detected in a chromosome-spread assay." (PMID 35918532, 2022). "Numerous SYCP3 alterations have been observed in infertile women and men at the clinical level." (PMID 31671664, 2019). "The biological processes significantly represented among differentially expressed genes included mitochondrial function (Mrps31 and Trit1), cell senescence (Gpx6, Lamtor1 and Hist1h1e), cell growth (Hormad1 and Hormad2), infertility (Sycp3), and embryo development (Gli3)." (PMID 29851234, 2018). "The ratio of infertility genes expression: DDX5, TNP2, DDX3Y, TDRD6, SOHL2, DDX31, and SYCP3 in infertility cell (azoospermia) in comparison to a normal cell." (PMID 36241908, 2022). "However, to determine whether the SNP identified in the SYCP3 gene had an impact on the patient's 1 infertility, further experiments are required including differentiation towards meiotic or more mature germ cells and forced expression of SYCP3 using specific lentiviral vector for instance." (PMID 35995809, 2022). "Although it is not known whether the remaining genes may lead to female infertility, it is noteworthy that in seven of them (ADAD2, AR, C1orf146, MLH3, RAD21L1, SYCP3, and TERB1), the corresponding female KO mice are infertile." (PMID 40896145, 2025).
male infertility (11 papers, 2014 to 2024). The inability of the male to effect fertilization of an ovum after a specified period of unprotected intercourse. "For example, the mutation of SYCP3 causes male infertility with complete meiotic prophase arrest." (PMID 36910159, 2023). "There are also male infertility cases caused by defects in single genes including CFTR, DDX3Y, SYCP3, TEX11, AURKC, and DPY19L2, but the number of genes confidently linked to male infertility remains very low." (PMID 34190021, 2022). "In existing studies, SYCP2 was reported as a robust candidate gene for male infertility since its encoding protein can interact directly with protein products of the male infertility genes TEX11 and SYCP3 in mice." (PMID 36159998, 2022). "Other genes related to male infertility were identified to associate with azoospermia (e.g., SOHLH1, SYCP3, and TEX11)." (PMID 34442404, 2021). "At the moment, only three autosomal dominant genes are moderately linked to isolated male infertility: doublesex and mab-3 related transcription factor 1 (DMRT1), kelch like family member 10 (KLHL10) and synaptonemal complex protein 3 (SYCP3)." (PMID 30865283, 2019). "We mainly describe the SYCP3 and PLK4 genes that we have studied in our laboratory, and add comments on other genes associated with human male infertility." (PMID 29259455, 2017). "In this review, the SYCP3 and PLK4 genes that have been studied in the authors’ laboratory are mainly described and comments on other genes that are associated with human male infertility have been added." (PMID 29259455, 2017). "Additionally, the coiled-coil domain of murine SYCP2 interacts with SYCP3 and TEX11, which are themselves implicated in human male infertility." (PMID 39202451, 2024). "Genes SYCP3 and DDX4, which contained both hypo-DMRs and hypo-DMCs identified in our study, play a major role in spermatogenesis insofar as either mutation or aberrant methylation of these genes associate to male infertility." (PMID 29843609, 2018). "Also, the absence of SYCP3 results in Azoospermia, suspended spermatogenesis, and male infertility." (PMID 31671664, 2019).
Azoospermia (6 papers, 2017 to 2023). Absence of any measurable level of sperm,whereby spermatozoa cannot be observed even after centrifugation of the semen pellet. "This situation holds for genes such as MPC2, associated with schizophrenia, SYCP3, with azoospermia, and NAT8, with chronic kidney disease." (PMID 32392208, 2020). "Many researchers have analyzed genes in the AZF region on the Y chromosome; however, in 2003 the SYCP3 gene on chromosome 12 (12q23) was identified as causing azoospermia by meiotic arrest through a point mutation." (PMID 29259455, 2017). "Similar to our results, UCB-MSCs increased meiosis-related genes in chemotherapeutic-induced azoospermia mice, and SYCP3 expression in busulfan-induced azoospermia could also be restored by UCMSCs transplantation." (PMID 37574561, 2023).
cyst (3 papers, 2022 to 2025). A sac-like closed membranous structure that may be empty or contain fluid or amorphous material. "In support of selective sharing, recent work in mouse testes showed that certain mRNAs are always shared between sister cells in cyst (e.g., Sycp3), others are only partially shared (e.g., Ccdc28a), and some are never shared (e.g., Smok2b)." (PMID 41213017, 2025). "Specifically, the analysis of SYCP3 and H1t showed that cells contained in cyst are arrested in late-pachytene and diplotene-like stages." (PMID 35768632, 2022).
breast carcinoma (2 papers, 2020). "According to Kaplan–Meier plotter, low expression of CD109, ID4, NR4A1, and SYCP3 is associated with poor RFS in breast cancer patients." (PMID 32679794, 2020). "SYCP3 is overexpressed in various human breast cancer cell lines, and EMSY is amplified almost exclusively in sporadic breast and ovarian cancers, suggesting that overexpression of SYCP3 and EMSY phenocopies cancer related-BRCA2 mutations." (PMID 32345962, 2020).
cervical cancer (2 papers, 2014 to 2022). A primary or metastatic malignant neoplasm involving the cervix. "The clinical relevance of SYCP3 expression was described in cervical cancer and NSCLC." (PMID 35251135, 2022).
lymph node metastasis (2 papers, 2017 to 2022). "Immunohistochemical and tissue microarray analysis of NSCLC patient samples revealed high cytoplasmic SYCP3 expression, which correlates with early stage NSCLC, lymph node metastasis, pleural invasion and poor survival." (PMID 35251135, 2022).
lymphoma (2 papers, 2006 to 2022). A malignant (clonal) proliferation of B- lymphocytes or T- lymphocytes which involves the lymph nodes, bone marrow and/or extranodal sites.
seminoma (2 papers, 2013 to 2025). A radiosensitive malignant germ cell tumor found in the testis (especially undescended), and extragonadal sites (anterior mediastinum and pineal gland). "Concurrent with this delayed maturation is the expression of meiotic genes including NOTCH and SYCP3 in both CIS cells as well as seminoma cells." (PMID 24555040, 2013).
Telangiectasia (2 papers, 2017 to 2018). Telangiectasias refer to small dilated blood vessels located near the surface of the skin or mucous membranes, measuring between 0.5 and 1 millimeter in diameter. "The analysis of synapsis on the sex chromosomes, following SYCP3 (synaptonemal complex protein 3) and CREST (Calcinosis Raynaud’s phenomenon, Esophageal dysmotility, Sclerodactyly, and Telangiectasia) immunostaining, revealed unexpected results." (PMID 29794981, 2018).
colorectal carcinoma (1 paper, 2022). A malignant epithelial neoplasm that arises from the colon or rectum and invades through the muscularis mucosa into the submucosa. "It was reported that SYCP3 expression can be induced in the colorectal carcinoma cell line DLD1 after treatment with the demethylating agent 5-azacytidine, indicating that SYCP3 expression in mitotic cells is regulated by a demethylation-dependent process, similarly to other meiotic genes." (PMID 35251135, 2022).
germ cell tumor (1 paper, 2021). A benign or malignant, gonadal or extragonadal neoplasm that originates from germ cells. "As for SYCP3, its role in meiosis and germ cell development is well‐established, being frequently interpreted as a marker of meiotic progression in germ cell tumors." (PMID 33513287, 2021).
non-small cell lung carcinoma (1 paper, 2017). A group of at least three distinct histological types of lung cancer, including non-small cell squamous cell carcinoma, adenocarcinoma, and large cell carcinoma. "We aimed to investigate the possible lymphangiogenic significance of synaptonemal complex protein 3 (SCP3) in non-small cell lung cancer (NSCLC)." (PMID 28623914, 2017).
Renal cyst (1 paper, 2025). A fluid filled sac in the kidney. "Further examination of differentially expressed genes in renal cysts and SC transplants demonstrated significant downregulation of key meiotic proteins, including Sycp3 and Sycp1, as well as defects in DSB-related proteins Rad51 and Spo11, which align with our previous findings." (PMID 40386496, 2025).
Sézary Syndrome (1 paper, 2019). "Our results show significant differential gene expression of STAG3, SGO2, SYCP3, and DMC1 in a cohort of Sézary Syndrome patients when compared to healthy controls." (PMID 31214493, 2019).
cancer (10 papers, 2006 to 2025). A tumor composed of atypical neoplastic, often pleomorphic cells that invade other tissues. "SYCP3 expression has been linked to immune resistance and enhanced cancer stemness through Akt-mediated upregulation of anti-apoptotic molecules and Nanog." (PMID 38596293, 2024). "SYCP3 is a DNA‐binding protein and a structural component of the synaptonemal complex, and SYCP3‐mediated PI3K/Akt activation appears to be highly associated with resistance of tumor cells to cancer drugs." (PMID 25413326, 2014). "We found a greatly down‐regulated SYCP3 gene encoding the synaptonemal complex protein 3, which is a marker for cell transformation that has prognostic significance in various cancers." (PMID 25413326, 2014). "Examples include the HORMAD1/2, MND1, MEIOB and SYCP3 genes, which directly influence the HR activity of cancer cells." (PMID 35251135, 2022). "SYCP3 is a meiosis‐specific gene, but also expressed in several cancer types, in which it impairs mitotic recombination by interfering with BRCA2, sensitizing certain tumor cells to PARPis; hence, we wanted to investigate this in TGCTs as well." (PMID 33513287, 2021). "Normal expression of SYCP3 is limited to meiotic cells, but emerging evidence shows an abnormal expression of SYCP3 in many cancers." (PMID 34440403, 2021). "In silico analysis of public databases confirmed SYCP3 overexpression in normal testis (versus other tissues/organs), both at RNA and protein levels, and also in TGCTs compared to other cancer types." (PMID 33513287, 2021). "The realization that meiotic gene products, including SYCP3, are upregulated in a number of cancers further highlights the importance of these studies to understand the pathological mechanisms that contribute to genomic instability in human cells." (PMID 31615332, 2019). "Overexpression of SYCP3 has been reported in some types of cancer." (PMID 31615332, 2019). "Additionally, SYCP3 may also function in cancer cells and modulate genome integrity." (PMID 40488283, 2025). "Interestingly, when abnormally produced in mitotically dividing cells, the SYCP3 can impair recombination and drive ploidy changes that affect chromosome segregation in cancer cells, which may be one of the mechanisms that led to the hyperploidy of MtrBTN2 cells." (PMID 37816387, 2023). "More studies are needed to understand how SYCP3 interacts with both BRCA2 and RAD51 and the impact on the BRCA2-RAD51 interactions in cancer cells and meiotic cells." (PMID 34440403, 2021). "Expression of SYCP3 has been reported in various cancers including cervical cancer, acute lymphoblastic leukemia, non-small cell lung cancer, ovarian cancer and astrocytoma and is associated with shorter overall survival." (PMID 38596293, 2024). "Sparse information is available on the role of SYCP3 in tumor genomic integrity except that is binds to BRCA2, which subsequently inhibits RAD51-dependent homologous recombination and confers hypersensitivity of cancer cells to PARP inhibition." (PMID 38596293, 2024).
tumor (6 papers, 2014 to 2023). "Germ cell markers (Ddx4, Sycp3) were significantly reduced in tumours, indicating the paucity of germ cells in these areas." (PMID 37564373, 2023). "Mechanistically, SYCP3 expression outside the meiotic context has been shown to disrupt the activity of the tumor-suppressing recombination regulator BRCA2." (PMID 35251135, 2022). "Axial components include SYCP3, the presence of which is frequently used as a molecular marker for meiotic progression in GC tumours (for example, see Jørgensen & Rajpert‐De Meyts, 2014)." (PMID 31102330, 2019). "Whilst I'm not aware that this has been studied extensively in germ line tumours, SYCP3 does become expressed in germ line tumours, so disruption of BRCA2 activity in germ line tumours by meiotic factors is an interesting possibility." (PMID 31102330, 2019). "Moreover, SYCP3 expression was correlated with increased sensitivity to Olaparib in several somatic tumor cell lines." (PMID 33513287, 2021). "A body of emerging evidence has revealed that meiotic chromosome regulator genes, including REC8, SMC1β, RAD21L1, TEX19, HORMAD1, and SYCP3, are inappropriately activated to modulate chromosome maintenance and segregation in tumor development, maintenance, and spread." (PMID 34150762, 2021).
infection (3 papers, 2016 to 2023). The state of being infected such as from the introduction of a foreign agent such as serum, vaccine, antigenic substance or organism. "Nevertheless, the infection was also able to repress cell cycle related genes, such as cyclin G1 (CCNG1), regulator of cell cycle (RGCC), and synaptonemal complex protein 3 (SYCP3)." (PMID 27197554, 2016).
SYCP3 also shares sentences with these, for which no sentence is quoted: Testicular atrophy (2 papers); cervical intraepithelial neoplasia (1); chronic kidney disease (1); Fanconi anemia (1); female infertility (1); glioma (1); heart failure (1); Ovarian Insufficiency (1); schizophrenia (1); Sertoli Cell-Only Syndrome (1); tuberculosis (1); vitamin A deficiency (1).